FADS1 (fatty acid desaturase 1)
Diseases named in the same sentence as FADS1 in open-access papers (continued):
Sharing a sentence is not in itself a finding about the gene and the disease.
gastric cancer (continued). "In conclusion, we observed a significant inverse association between dietary DHA and the risk of gastric cancer but found that FADS1 rs174546 and FADS2 rs174583 did not modify the association between dietary n-3 or n-6 PUFAs and gastric cancer risk." (PMID 29491470, 2018). "However, we did not identify a significant modifying effect according to FADS1 rs174546 or FADS2 rs174583 genetic variants on the association between n-3 or n-6 PUFAs and the risk of gastric cancer." (PMID 29491470, 2018). "In particular, intestinal-type gastric cancer (GC) cells express extremely low levels of ELOVL5 and FADS1 due to hypermethylation at the promoter region and are resistant to ferroptosis, while mesenchymal-type GC cells are sensitive to ferroptosis at high levels of ELOVL5 and FADS1." (PMID 33801564, 2021).
type 2 diabetes (17 papers, 2010 to 2025). "In supporting this, a human study showed that the higher FADS1 activity was associated with a lower risk of type 2 diabetes." (PMID 38732052, 2024). "To satisfy the independence assumption, we excluded the genetic variants located on the GCKR or FADS1 genes as previously, because these genes are strongly associated with other traits relevant to type 2 diabetes." (PMID 36624450, 2023). "FADS1 activity was significantly associated with an increased risk of type 2 diabetes in Japanese population." (PMID 36712514, 2022). "We also considered overall consumption of nuts and seeds, although their composition, association with type 2 diabetes risk, and potential for interaction with FADS1/2 genotypes may vary within this group." (PMID 40484934, 2025). "However, we did not observe a statistically significant interaction of nut consumption with FADS1 in relation to type 2 diabetes risk." (PMID 40484934, 2025). "However, with regard to FADS1, we have only tested the most significant metabolite ratios for their association with type 2 diabetes." (PMID 28729637, 2017). "Our results are broadly in agreement with those of previous smaller studies of the associations of FADS1 and FADS2 genetic variants or Δ-5 and Δ-6 desaturase activities with type 2 diabetes." (PMID 31690987, 2020). "This study examined influence of FADS1 and FADS2 genetic variants on desaturase activities and blood lipid concentrations in type 2 diabetes patients, and further assessed their interrelationships." (PMID 28555039, 2017). "Nevertheless, two SNPs (FADS1, REV3L) which were associated with metabolite traits were significant in bigger consortia for type 2 diabetes, such as DIAGRAM2 or GoT2D14." (PMID 28729637, 2017). "In large meta-analyses, associations between FADS1-2-3 and carotid intima media thickness, AGPAT1 and type 2 diabetes, and APOA1 and coronary artery disease were observed." (PMID 22359512, 2012). "We explored whether FADS1 variants influence the relationships of LA and α-linolenic acid (ALA) intakes and nut consumption with plasma phospholipid fatty acid profiles and type 2 diabetes risk in a large-scale cohort study and a randomized controlled trial." (PMID 40484934, 2025). "In the EPIC-InterAct case-cohort (7,498 type 2 diabetes cases, 10,087 subcohort participants), we investigated interactions of dietary and plasma phospholipid fatty acids and nut consumption with FADS1 rs174547 in relation to incident type 2 diabetes using weighted Cox regression." (PMID 40484934, 2025). "As for potential biological mechanisms, the associations of plasma fatty acid levels and genetic variations in FADS1/2 with type 2 diabetes may be mediated by impaired glucose tolerance and beta cell dysfunction, as suggested by the present MR study." (PMID 31690987, 2020). "FADS1 was reported to be related to type 2 diabetes by a previous GWAS study, but the mechanism was still unknown." (PMID 30110382, 2018). "Although the associations between the SNPs in MADD, ADRA2A, C2CD4B, IGF1, IRS1and FADS1 with fasting glucose or type 2 diabetes were directionally consistent with those observed for white Europeans and of similar magnitude to that observed in the previous GWAS, none reached nominal significance." (PMID 21747906, 2011). "In summary, we identified a novel metabolite locus (MOGAT2) in single variant analyses and four genes (GFRAL, BIN1, TFRC, OR51Q1) within gene-based tests and could show that two previously known mGWAS loci (FADS1 and REV3L) might be relevant for the risk of type 2 diabetes." (PMID 28729637, 2017). "In this study, we genotyped SNPs (FADS1: rs174547, rs174548, rs174550; FADS2: rs174575, rs174576, rs174583, rs498793 and rs2727270) in 820 patients with type 2 diabetes and compared our findings with those reported in HapMap in a healthy population." (PMID 28555039, 2017).
type 2 diabetes (continued). "Selected SNPs (FADS1: rs174547, rs174548, rs174550; FADS2: rs174575, rs174576, rs174583, rs498793 and rs2727270) were genotyped in 820 type 2 diabetes patients and compared with those reported in the HapMap." (PMID 28555039, 2017). "This study found FADS1 rs174547 and FADS2 rs2727270 genotypes were significantly correlated with decreased D5D and D6D activities and decreased HDL-C concentrations in patients with type 2 diabetes." (PMID 28555039, 2017). "SNPs in or near MADD, ADRA2A, PROX1, FADS1, C2CD4B, IGF1, and IRS1 did not exhibit significant associations with type 2 diabetes or related glycemic traits (P≥0.10)." (PMID 21747906, 2011). "In conclusion, FADS1 rs174547 and FADS2 rs2727270 genotypes were significantly correlated with decreased HDL-C concentrations, and D5D /D6D activities as estimated as 20:4(n-6)/20:3 (n-6) and 18:3 (n-6)/18:2 (n-6) in a linear pattern in patients with type 2 diabetes." (PMID 28555039, 2017).
breast carcinoma (15 papers, 2013 to 2025). "Metformin specifically reduces FADS1 activity and individuals with FADS1 genetic variants with reduced activity have decreased breast cancer risk." (PMID 36581893, 2022). "Recently, a report showed that FADS1 compensated for the functions of FADS2 on twenty-carbon fatty acids under FADS2-deficient conditions such as MCF-7 breast cancer cell conditions." (PMID 26742061, 2016). "Fatty acid desaturation by the delta-5 and delta-6 desaturases upregulated by Ets-1 in this study, fatty acid desaturase-1 and −2, result in the production of arachidonic acid, which is associated with breast cancer progression, metastasis and angiogenesis." (PMID 24280356, 2013). "In breast cancer cells, FADS1/2 have also been linked to inflammation via their production of arachidonic acid, suggesting that their suppression in MM-MSCs may be linked to an anti-inflammatory response linked to increased cytokine signaling." (PMID 33680918, 2020). "In addition, individuals with genetically determined lower fatty acid desaturase 1 (FADS1) activity due to the presence of the minor T allele will derive more benefit from n-3 LC-PUFAs, including a reduced risk of breast cancer, than those with higher FADS1 activity (G allele)." (PMID 35805595, 2022). "FADS1 knockdown significantly inhibited growth and metastasis in breast cancer." (PMID 38136676, 2023). "In human breast cancer MCF7 cells, loss of FADS2 function blocks normal polyunsaturated fatty acid biosynthesis resulting in the FADS1 generation of polyunsaturated fatty acids which lack the 8–9 double bond of eicosanoid signaling precursors (i.e., arachidonic acid and eicosapentaenoic acid)." (PMID 26445145, 2015). "Therefore, investigating the interplay between omega-3 supplementation and FADS1/FADS2 genotypes in breast cancer could provide valuable insights into personalized dietary interventions and therapeutic strategies." (PMID 40430008, 2025). "Moreover, since a recent study reported that anti-estrogen therapy sensitizes estrogen receptor-positive (ER+) breast cancer to ferroptosis, we explored whether endocrine therapy could induce ferroptosis by a mechanism involving FADS1/2 axis." (PMID 38926633, 2024). "The two most up-regulated AR responsive genes FADS1 and KRT19 are likely to be targets of both AR and ERβ, where FADS1 has been shown to be regulated by estrogen, and KRT19 expression correlating to estrogen receptor expressing breast cancer." (PMID 32413024, 2020). "Similarly, delta-5 desaturase, coded for by the FADS1 gene in primates, showed desaturation activities on EDA and ETE in breast cancer cells, suggesting that delta-5 desaturase may play a role in replacing delta-6 desaturase in a delta-6 desaturation-deficient system." (PMID 26742061, 2016). "Breast tumors and breast cancer cell lines have reduced levels of delta-6 desaturase (FADS2) compared to non-malignant cells, as is delta-5 desaturase (FADS1) in non-small-cell lung cancer and esophageal squamous cell carcinoma." (PMID 33413672, 2021).
Insulin resistance (15 papers, 2013 to 2025). Increased resistance towards insulin, that is, diminished effectiveness of insulin in reducing blood glucose levels. "Although this was done to strengthen our candidate gene approach, one cannot rule out the many polymorphisms found in this gene cluster including the FADS1 rs174550 variant, which has been previously implicated in insulin resistance." (PMID 24455201, 2013). "Associations between FADS1 polymorphisms and insulin resistance in a population with European descent arose from a GWAS meta-analysis conducted by Dupuis and colleagues." (PMID 24455201, 2013). "Thus, the increased AT inflammation after dietary LA-enriched diet may predispose the subjects with the TT genotype of FADS1-rs174550 at higher risk for developing dysfunctional AT and insulin resistance." (PMID 35701670, 2022). "In fact, reduced liver FADS1 enzyme activity was also inversely correlated with homeostatic model assessment for insulin resistance in individuals with MASLD." (PMID 40044043, 2025). "A significant association between FADS1 and FADS2 haplotypes was found with insulin resistance while controlling for confounders." (PMID 24455201, 2013). "Despite these limitations, our study is the first to identify a relationship between a FADS1/2 haplotype and insulin resistance in a severely mentally ill population taking antipsychotics." (PMID 24455201, 2013). "Many studies suggest that delta-5-desaturase (D5D) activity (FADS1) is associated with a lower risk of T2D, while stearoyl-CoA desaturase 1 (SCD1) and delta-6-desaturase (D6D, FADS2) variants are linked with insulin resistance and worsening of glucose tolerance or an increased risk of T2D." (PMID 30453550, 2018). "We noted that FADS1 interacts with dietary intake, such as SSB and carbohydrate intake, possibly leading to insulin resistance, and others have proposed polyunsaturated fatty acids and fatty acid desaturase (FADS) activity." (PMID 41295283, 2025). "Higher expression of TCF7L2 and the fatty acid desaturases FADS1, FADS2 and SCD could contribute to insulin resistance." (PMID 26087292, 2015).
coronary artery disease (13 papers, 2009 to 2026). "T alleles and TT genotypes of the FADS1/FADS2 variants are associated with coronary artery disease and ischemic stroke." (PMID 35736500, 2022). "However, the associations were driven by FADS1, which was also significantly or suggestively associated with coronary artery disease, abdominal aortic aneurysm and aortic valve stenosis." (PMID 31817859, 2019). "Our results for FADS1 based on data from the CARDIoGRAMplusC4D consortium are in line with those of some prior smaller studies of the association of genetic variations in FADS1 or Δ5-desaturase activity with coronary artery disease." (PMID 31817859, 2019). "The GG genotype of the FADS1 variant rs174537 increases the risk of developing T2DM and coronary artery disease." (PMID 35736500, 2022). "It has been reported that the fatty acid desaturase 1 (FADS1) and FADS2 genes play an important role in the adaptation of the Inuit diet and are associated with coronary artery disease, and the variants in these genes may affect the biosynthesis of ω-3 FAs." (PMID 37121469, 2023). "Identifying the associated gene(s) from the genetic association evidence for the FADS1-2-3 locus in humans is complicated by the fact that multiple LD blocks have been associated with several different but related lipid traits, as well as coronary artery disease and nonfatal myocardial infarction." (PMID 19750004, 2009). "It was reported that the minor allele of genetic single nucleotide polymorphism (SNP) rs174547 in FADS1 gene was associated with increased triglyceride and decreased high density lipoprotein (HDL) cholesterol, as well as increased coronary artery disease (CAD) risk." (PMID 25849351, 2015).
depression (9 papers, 2019 to 2025). "For example, one of the risk locus in FADS1 we identified, significantly associated with depression, was under positive selection in a specific population." (PMID 40075226, 2025). "The odds ratio (OR) for allele T on rs174546 of FADS1 was significantly greater than 1 (OR = 1.015, p = 0.000856), indicating an increased risk of depression." (PMID 40075226, 2025). "Additionally, some depression-associated genes in the South Asian population are linked to diet and metabolism, such as FADS1, FADS2, LPIN3, and SGIP1." (PMID 40075226, 2025). "Our TWAS results showed that the expression of FADS1 largely explains the GWAS signal of depression, suggesting the power of TWAS to detect promising target genes." (PMID 34021117, 2021). "Another microarray study also found that FADS1 expression was downregulated in the prefrontal cortex of suicidal male major depression patients." (PMID 34021117, 2021). "Furthermore, FADS1 expression was shown to be reduced in the brain of patients with depression." (PMID 35743093, 2022). "Interestingly, a previous study has showed that mRNA expression of FADS1 was significantly lower in depression patients compared with controls, suggested that FADS1 may have pivotal roles in depression." (PMID 34021117, 2021). "Seven out of 53 risk genes (B3GALTL, FADS1, TCTEX1D1, XPNPEP3, ZMAT2, ZNF501 and ZNF502) showed TWS associations with depression in two independent brain expression quantitative loci (eQTL) datasets, suggesting that these genes may represent promising candidates." (PMID 34021117, 2021). "However, it is noted that mental health is recognised as one of the risk factors for MetS, therefore, it is possible that the association found between rs174547 in FADS1 gene and FBG in the previous study could be confounded by the presence of depression." (PMID 31340443, 2019). "Individual genes that commonly emerge among these studies include those with existing links to depression, such as DRD2 and FADS1, as well as novel genes such as NEGR1 and RPL31P12 without existing links to depression." (PMID 37076454, 2023). "Notably, our TWAS analysis suggested that the FADS1 gene may represent a promising candidate for depression (as the length of FADS1 was small compared with nearby genes, these smaller genes are often overlooked in GWAS because there are many larger protein-coding genes nearby)." (PMID 34021117, 2021). "Unlike the SNP in FADS1, the SNP in ZNF445 has an OR for allele T on rs2372688 of 0.98 (p = 0.000006758), suggesting a protective effect against depression." (PMID 40075226, 2025).
bipolar disorder (8 papers, 2018 to 2026). A disorder of the brain that causes unusual shifts in mood, energy, activity levels and the ability to carry out day-to-day tasks. "In an experimental study, mice with Fads1/2 gene knockouts were used to simulate the effect of the bipolar disorder (BIP) risk allele on Fads1/2 activity, revealing significant changes in lipid profile and behavioral alterations." (PMID 40865610, 2025). "Consistent with a past study that was conducted among patients with schizophrenia and bipolar disorder, the present study found that rs174547 in FADS1 gene was associated with FBG in vegetarians." (PMID 31340443, 2019). "Colocalization supported shared causal variants between many lipid traits and MDD, prominently at the FADS1/2 locus and additional loci, suggesting multiple entry points into lipid metabolism that differ partly from bipolar disorder." (PMID 42196323, 2026). "SNPs in the FADS1/2 region have been reported to be associated with circulating PUFA levels and the risk of bipolar disorder in different populations." (PMID 40865610, 2025). "RPS17 also demonstrated strong evidence for colocalization between the TWAS weights and schizophrenia in the PsychENCODE cortical dataset (PPH4 = 0.953), which was also seen for FADS1 and bipolar disorder (PPH4 = 0.95)." (PMID 36055211, 2022).
laryngeal squamous cell carcinoma (8 papers, 2017 to 2024). A squamous cell carcinoma that arises from the larynx. "Recently, a genome-wide association study (GWAS) identified a new susceptibility loci at fatty acid desaturase 1 (FADS1) gene (rs174549) associated with laryngeal squamous cell carcinoma (LSCC) in Chinese population." (PMID 28178666, 2017). "Higher FADS1 levels in the lung tissues were associated with LUAD risk, which is consistent with its role in increasing the proliferation and migration of laryngeal squamous cell carcinoma through activation of the Akt/mTOR pathway." (PMID 37236969, 2023). "FADS1 has emerged as mediator of lipid metabolism gene and drives laryngeal squamous cell carcinoma progression by activating AKT/mTOR signaling pathway." (PMID 33277966, 2021). "FADS1 can promote the progression of laryngeal squamous cell carcinoma by activating the AKT/mTOR signaling pathway." (PMID 34706720, 2021). "Previous work has shown that FADS1 supports laryngeal squamous cell carcinoma progression, while reduced Δ5 desaturase may predict poorer outcomes in non–small cell lung cancer." (PMID 38522521, 2024). "Moreover, not only FADS1 expression, but also certain SNPs of FADS1, such as rs174549, rs174548, and rs174550 have been identified as independent and favorable factors in predicting oral, lung, colorectal cancers, and laryngeal squamous cell carcinoma progression." (PMID 34438249, 2021).
colon cancer (7 papers, 2018 to 2025). "Subjects on a Mediterranean diet with all major alleles for the FADS1/2 genes had 16% lower AA concentrations in the colon mucosa, suggesting a reduced colon cancer risk due to lower PGE2 production." (PMID 40430008, 2025). "Our example for miR-1908-5p, FADS1, and benign neoplasm of colon serves as an example of the latter." (PMID 39434104, 2024). "The oncogenic properties of FADS1 have also been shown in HCA-7 (colon cancer) and BxPC-3 (pancreatic cancer cells)." (PMID 32392704, 2020). "Colocalisation analysis suggested a shared causal variant between benign neoplasm of colon and miR-1908-5p (PP H4 = 0.58), but not for FADS1 (PP H4 = 0.008)." (PMID 39434104, 2024). "In the Mendelian randomisation analysis, we find a protective causal effect of miR-1908-5p on the risk of benign colon neoplasm and show that this effect is independent of its host gene (FADS1)." (PMID 39434104, 2024). "Together with FADS2 and FADS1, levels of ELOVL2 and 5 have been found to be increased in colon tumors." (PMID 34206240, 2021). "For this reason, the expression of FADS1 and FADS2 is increased in some cancers, e.g., Lewis lung carcinoma, melanoma, colon cancer, hepatocellular carcinoma, and breast cancer." (PMID 32392704, 2020). "The presence of a shared genetic signal between miRNA and host gene raised the question of whether the effect identified between miR-1908-5p and benign neoplasm of the colon has been driven by FADS1 rather than miR-1908-5p." (PMID 39434104, 2024).